CRP (C-reactive protein)
Diseases named in the same sentence as CRP in open-access papers (continued):
Sharing a sentence is not in itself a finding about the gene and the disease.
dementia (continued). "Thus, during the CRP measurement, participants developing dementia might have been in the prodromal stage of the syndrome, which has been associated with lowered CRP levels, potentially explaining the current null findings." (PMID 38706574, 2024). "Therefore, it could be speculated (although published data is not yet available to prove this hypothesis) that other diseases causing elevated CRP may increase the risk of dementia." (PMID 36776896, 2023). "Therefore, we aimed to investigate whether there might be an association between chronic inflammation, defined by measurement of circulating CRP in chronic inflammatory diseases, and a higher risk of developing dementia or cognitive decline." (PMID 36776896, 2023). "Interestingly, a recent longitudinal study in aging men found that sleep disturbances, but not daytime tiredness or sleep duration, were associated with a 58% increase in dementia after adjusting for known metabolic and inflammatory risk factors (e.g. C-reactive protein), and physical activity." (PMID 31647051, 2020). "Accumulating evidence points towards CRP, especially its monomeric form, as playing an active role in neurodegenerative diseases like AD and dementia." (PMID 40943152, 2025). "The present study used an epigenetic and proteomic approach to characterize two measures of chronic inflammation—CRP and GDF15 DNAm—and examine their associations with structural brain and cognitive trajectories, as well as dementia risk." (PMID 41274863, 2025). "A narrative synthesis was structured according to the identified clusters across studies, their associations with dementia risk, and any moderation or stratification analyses for APOE ε4 allele carriership and C‐reactive protein (CRP), among others." (PMID 40990184, 2025). "Studies have described increased levels of inflammatory markers like C reactive protein (CRP) and interleukin (IL)-6 in dementia patients." (PMID 40051432, 2025). "CRP appears to play a multifaceted role in the pathogenesis of AD, dementia, and cognitive dysfunction by promoting amyloid plaque formation, disrupting the blood–brain barrier and amplifying neuroinflammatory and vascular injury responses." (PMID 40943152, 2025). "The ACE, REN, APOE, CRP, and IL6 proteins obtained through this bioinformatic approach appear to be associated with both HF and dementia." (PMID 40699836, 2025). "Elevated levels of IL-6, CRP, and ACT in blood samples have been associated with an increased risk of developing dementia." (PMID 41294487, 2025). "In a recent study, the relationship between hs-CRP concentration and performance on a global measure of cognitive function was observed to vary across different stages of dementia progression." (PMID 39807297, 2025). "Peripheral inflammatory markers, including cytokines and C-reactive protein (CRP), as well as cerebrospinal fluid (CSF) indices, have been implicated in the onset and severity of neuropsychiatric manifestations in dementia." (PMID 41523330, 2025). "Of the genes/proteins associated with dementia, six are consistent with the results obtained from VOSviewer: APP, MAPT, APOE, ACE, IL6, and CRP." (PMID 40699836, 2025). "Secondly, higher SB levels were associated with higher levels of CRP, interleukin 6, tissue plasminogen activator which are the marker of inflammation-induced diseases such as cancer, CAD, COPD, dementia." (PMID 40177096, 2025). "Looking at the role of CRP in dementia, it has been shown that CRP is upregulated in the brains of AD patients, both at the protein and the mRNA level." (PMID 39358806, 2024). "On average, participants with incident dementia had higher levels of CRP (5.1 μg/mL), compared to participants with normal cognition (4.3 μg/mL)." (PMID 39003383, 2024). "Further, there is a correlation between elevated levels of interleukin (IL)-6 and C-reactive protein (CRP) and chronic low-grade inflammation, which, in turn, increases the risk of all-cause dementia by 37% and 40%, respectively." (PMID 39193464, 2024).
dementia (continued). "One meta-analysis investigated that chronic inflammatory diseases, elevated CRP, and other inflammatory factors increase vascular permeability, penetrate the blood–brain barrier, and infiltrate the brain, potentially developing dementia." (PMID 38737864, 2024). "One interpretation for these null findings pertains to the potential differential predictive value of CRP for different dementia subtypes." (PMID 38706574, 2024). "Higher levels of C-reactive protein (CRP), a marker of inflammation, have been correlated with more sleep fragmentation and high risk of dementia." (PMID 39851389, 2024). "We found that 14% of the observed disparity in incident dementia was accounted for by the interaction between minoritized group membership and elevated CRP, and 3% of the disparity was mediated by high CRP." (PMID 39003383, 2024). "We revised these sensitivity analyses in light of our main mediation models, and provide a comprehensive conceptualization for the use of CRP as a potential pathway to understand disparities in incident dementia among racialized social groups." (PMID 39003383, 2024). "Inflammatory markers C-reactive protein (CRP) and interleukin-6 (IL-6), which are also often elevated following a fracture, have been associated with an increased risk of all-cause dementia." (PMID 38334917, 2024). "Nevertheless, given the long subclinical phase of dementia, it remains possible that lifestyle behaviours and CRP levels were affected by subclinical dementia processes." (PMID 38706574, 2024). "For instance, increases in systemic levels of the inflammatory markers IL-6 and CRP are associated with MCR, a condition involving a remarkable risk of progression toward dementia." (PMID 38337499, 2024). "For example, among those with CRP levels ≥4.73 μg/mL (≥75th percentile), the 6-year cumulative dementia incidence was 13%, and among those with CRP levels <0.98 μg/mL (<25th percentile) was 12%." (PMID 39003383, 2024). "We included potential confounders of the association between our exposure of interest, racialized groups, our mediator CRP, and incident dementia, with all confounders measured at baseline." (PMID 37066239, 2023). "The results displayed that the odds ratio for IBD and dementia was 1.91 [1.15-3.15], for RA it was 1.90 [1.09-3.32] following sensitivity analysis and for CRP it was 1.62 [1.22-2.15]." (PMID 36776896, 2023). "On average, participants with incident dementia had higher levels of CRP (5.1μg/mL), compared to participants with normal cognition (4.0μg/mL)." (PMID 37066239, 2023). "As for dementia diagnosis, Song and Colleagues found significantly elevated CRP levels in patients with AD compared with healthy controls." (PMID 37467176, 2023). "We found that 12% of the observed disparity in incident dementia was accounted for by the interaction between minoritized group membership and elevated CRP, and 2% of the disparity was mediated by high CRP." (PMID 37066239, 2023). "For example, among those with CRP levels ≥ 4.57μg/mL (≥ 75th percentile), the 6-year cumulative dementia incidence was 17%, and among those with CRP levels < 0.96μg/mL (< 25th percentile) was 15%." (PMID 37066239, 2023). "For the dementia diagnosis, the CRP-only score only remained a significant predictor for the highest quartile, whereas WBC appeared to be a more robust predictor with similar effect sizes to the composite score." (PMID 37467176, 2023). "Inflammatory markers such as tumor necrosis factor (TNF), interleukin-6 (IL-6), chitinase-3-like protein 1 (CHI3L1 or YKL-40), and acute phase C reactive protein (CRP) were found to have effects on the brains or peripheral regions of dementia patients." (PMID 37873875, 2023). "Several agents have been used to model neuroinflammation-based neurodegeneration and dementia in AD, including lipopolysaccharide (LPS), streptozotocin, and monomeric C-reactive protein." (PMID 38260026, 2023).
dementia (continued). "Therefore, greater priority should be provided to the effective control of inflammation in patients with chronic inflammatory or autoimmune conditions and further long-term assessment of circulating CRP might inform of an individual’s relative risk of developing dementia." (PMID 36776896, 2023). "We examined the distributions of all baseline covariates by each of self-reported racialized categories, quartiles of the CRP distribution, and incident dementia using bivariate statistical tests, as appropriate." (PMID 37066239, 2023). "Although we found consistent evidence that CRP was an important mediator of racialized disparities in dementia, our research was limited to a baseline measurement and a unique biomarker." (PMID 37066239, 2023). "In the AFT models, 1 SD higher BMI, CRP, and HDL-c were significantly associated with a longer dementia free time." (PMID 36192662, 2022). "Several epidemiologic studies have shown a rather consistent association between systemic inflammatory markers (i.e., high-sensitivity C-reactive protein, tumor necrosis factor-alpha, and interleukin-6) and dementia or cognitive impairment." (PMID 35160273, 2022). "The individual-level data are based on a well-characterized sample, with measures of both BMI, WHR, CRP, and lipid levels, together with dementia information both from the data collections and through linkage to nationwide disease registers." (PMID 36192662, 2022). "It was found that elevated levels of inflammatory markers such as C-reactive protein (CRP) and Interleukin-6 (IL-6) are associated with loss of skeletal muscle mass, strength and an increased risk for dementia." (PMID 35794312, 2022). "Future studies investigating the role of CRP levels and cellular immunophenotyping in dementia should conduct a formal sample size calculation and would benefit from enrollment of larger numbers of patients per study group." (PMID 36358351, 2022). "The present study sought to investigate the role of WBC populations, platelet counts, derived hematological parameters such as NLR and PLR, and CRP levels as potential biomarkers for the differential diagnosis of dementia." (PMID 36358351, 2022). "Associations between body-mass index (BMI), waist-hip ratio (WHR), C-reactive protein (CRP), lipid levels, and dementia were tested in survival and mediation analyses." (PMID 36192662, 2022). "In general, however, the role of peripheral blood cells and inflammatory markers such as CRP in dementia has scarcely been studied, with most available studies being limited to investigations in patients with AD." (PMID 36358351, 2022). "Presence of dementia was the strongest predictor of delirium, followed by age at admission, CRP, and GCS." (PMID 35204633, 2022). "Critical care admissions were more likely with greater illness severity, CRP, or ferritin or BMI < 18.5 or ≥30, and less likely with age, frailty and dementia." (PMID 33543243, 2021). "Multivariate analyses showed that lower BMI, lower C-reactive protein, a lower ratio of homestay before hospitalization, a higher complication rate of cerebrovascular disease, dementia, and neuromuscular disease were significant characteristics of AP patients." (PMID 34329339, 2021). "In our multivariate model for mortality, age, dementia, peak C-reactive protein (CRP) levels, and mechanical ventilation were found to be statistically significant predictors of mortality." (PMID 33575135, 2021). "In multivariate analysis, lower BMI, lower C-reactive protein, a lower ratio of homestay before hospitalization, a higher complication rate of cerebrovascular disease, dementia, and neuromuscular disease were noted as a characteristic of AP patients." (PMID 34329339, 2021). "Lower BMI, lower C-reactive protein, a lower ratio of homestay before hospitalization, a higher complication rate of cerebrovascular disease, dementia, and neuromuscular disease were significant characteristics of AP patients compared with non-AP patients." (PMID 34329339, 2021).
dementia (continued). "Certain peripheral, as well as CSF inflammatory markers, such as IL-6 and C-reactive protein (CRP) have been reported to forecast dementia or decline in cognitive functions many years before their onset." (PMID 32391019, 2020). "Greater age, lower serum albumin levels, higher C-reactive protein levels, and severe dementia were reported as poor prognostic factors after PEG." (PMID 31577813, 2019). "A similar finding was observed in elderly individuals with dementia where an increased level of TNFα molecule was positively correlated with sTNFRII, IL-6, and C-Reactive Protein." (PMID 31178745, 2019). "The strength of this study was its longitudinal follow-up for incident cases of dementia that was preceded by multiple measurements of CRP with an interval between CRP measurements of 6 to 16 years." (PMID 30646251, 2018). "Reports also show that dementia is related to peripheral pro-inflammatory factors released by periodontal inflammatory mediators such as C-reactive protein, IL-6, haptoglobin, TNF-α, and fibrinogen." (PMID 29740354, 2018). "Our study yielded no significant findings for CRP in PD samples, although others have described higher CSF CRP values in patients with PD with dementia than in patients with PD and control patients." (PMID 29482610, 2018). "CRP values have already been pointed out as possible predictors of dementia in the elderly, especially in those with pre-existing cardiovascular disease." (PMID 28659812, 2017). "A study found that elevated CRP levels predate by 25 years the clinical onset of dementia, suggesting that inflammatory process occurs long before clinical symptoms appear." (PMID 24587705, 2014). "In conclusion, while elevated levels of CRP in mid- and early late-life predict subsequent cognitive impairment and dementia, this role appears to be reversed in the very old." (PMID 24305621, 2014). "CRP plays a wide role in the development of cardiovascular complications, dementia, cognitive impairments and Alzheimer’s disease." (PMID 24044608, 2013). "In dementia patients, CRP and SAA participate in diverse cellular functions including stress, depression and cognitive neuronal disorders." (PMID 24044608, 2013). "This lack of specificity means that elevated CRP levels do not uniquely indicate neuroinflammation or neurodegenerative processes associated with dementia." (PMID 39913250, 2025). "Third, the predictive value of CRP for dementia may be influenced by the timing and duration of inflammation." (PMID 39913250, 2025). "Since most of the identified proteins are not present in both diseases, we performed two independent PPI analyses: the first using the proteins associated with HF (NPPB, REN, ADIPOQ, VWF, ACE, IL6, and CRP) and the second using the proteins involved in dementia (CRP, APP, MAPT, APOE, ACE, and IL6)." (PMID 40699836, 2025). "The current study provides evidence that epigenetic proxies of CRP and GDF15 exposure reflect the activation of immune/inflammation‐related pathways and are associated with longitudinal brain atrophy and cognitive decline as well as long‐term dementia risk." (PMID 41274863, 2025). "The association between neuropsychiatric, cardiovascular, and sensory impairment/cancer clusters and dementia was notably stronger in the group with high CRP levels, with HRs of 2.69 (95% CI: 1.19–6.09), 2.34 (95% CI: 1.08–5.09), and 1.92 (95% CI: 1.02–3.63), respectively." (PMID 40990184, 2025). "Contrarily to cognitively healthy populations, previous reports have suggested that higher CRP may have a protective effect (i.e. in slowing decline) once individuals have a dementia diagnosis." (PMID 39807297, 2025). "For example, among minoritized participants, high CRP was associated with 1.26 (95% CI: 0.98, 1.62) times higher risk of incident dementia than low CRP, although this finding was not statistically significant." (PMID 39003383, 2024).
dementia (continued). "Our results suggest that even though non-Hispanic Black participants had higher levels of CRP than their non-Hispanic white counterparts, their risk of dementia was not statistically significant when comparing those with high CRP to those with low CRP." (PMID 39003383, 2024). "In a 2-year longitudinal study, an increased CRP levels were linked to the functional decline of caregivers to individuals with dementia but not to non-caregivers." (PMID 39297507, 2024). "The age- and sex-adjusted prevalence of all-cause dementia, AD and non-AD increased significantly with rising serum hs-CRP levels (p for trend < 0.001, p for trend = 0.004, p for trend = 0.002, respectively)." (PMID 38548879, 2024). "Therefore, the relationships of serum high-sensitivity CRP (hs-CRP) with dementia including AD and with regions of interest of brain MRI were investigated." (PMID 38548879, 2024). "The lack of CRP-dementia association conflicts with several studies that linked higher levels of inflammatory markers, including CRP, with increased risk of all-cause dementia up to 25 years later." (PMID 38706574, 2024). "A further interpretation of the current absence of a CRP-dementia association concerns the potential U-shaped pattern of CRP levels across dementia development." (PMID 38706574, 2024). "In the present study, dementia ascertainment started one year after the CRP measurement." (PMID 38706574, 2024). "To assess systemic inflammation as a potential pathway linking exposure to racism and dementia disparities, we investigated the mediating role of C-reactive protein (CRP), a systemic inflammation marker, and the moderating role of the racialization process in incident dementia." (PMID 39003383, 2024). "While lifestyle behaviours were linked to subsequent CRP levels, increased CRP levels were not linked to a higher incidence of dementia and did not mediate the association between lifestyle and subsequent dementia risk." (PMID 38706574, 2024). "Additional research should investigate the effects of CRP on different dementia subtypes." (PMID 38706574, 2024). "When moderation analysis was conducted in individuals aged ≥ 60 years, the association with incident dementia or AD was stronger for most risk factors in non-APOE4 carriers than in APOE4 carriers but weaker for a mother’s history of dementia and C-reactive protein." (PMID 38378514, 2024). "If considering treatment resistance and consistent evidence via meta-analysis of cytokine change in MDD and dementia, only IL6, TNF, and CRP are implicated, though this may reflect the relative popularity of these molecules for study." (PMID 38175420, 2024). "Research suggests that CRP levels might be heightened decades before dementia onset and during its severe phase, while they might be lower during the immediate years before clinical symptom manifestation." (PMID 38706574, 2024). "Among non-Hispanic Black participants, the association between CRP and incident dementia was null (IRR: 1.00; 95%CI: 0.72, 1.37)." (PMID 39003383, 2024). "Among minoritized participants (i.e., non-Hispanic Black and/or Hispanic), high CRP levels ( ≥ 75th percentile or 4.73μg/mL) are associated with 1.26 (95%CI: 0.98, 1.62) times greater risk of incident dementia than low CRP ( < 4.73μg/mL)." (PMID 39003383, 2024). "We attribute these findings to the null association between CRP and incident dementia among non-Hispanic Black participants, for which we have other possible explanations." (PMID 39003383, 2024). "In support of this, prior studies with shorter follow-ups found no prospective CRP-dementia associations, while those with longer follow-ups (13–25 years) showed such associations." (PMID 38706574, 2024).